S100A12 (S100 calcium binding protein A12)
Diseases named in the same sentence as S100A12 in open-access papers (continued):
Sharing a sentence is not in itself a finding about the gene and the disease.
acute respiratory distress syndrome (11 papers, 2013 to 2023). Progressive and life-threatening pulmonary distress in the absence of an underlying pulmonary condition, usually following major trauma or surgery. "Another risk gene S100A12 is a novel inflammatory disease biomarker in acute respiratory distress syndrome (ARDS), interstitial lung disease (ILD), and COPD." (PMID 34194423, 2021). "Also in lung diseases, the increased expression of S100A12 in acute respiratory distress syndrome suggested that S100A12 is more important in the onset of neutrophil influx compared to stages of chronic inflammation." (PMID 32582175, 2020). "It has been found that S100A12 expression in lungs, bronchoalveolar lavage fluid, and serum of patients with acute respiratory distress syndrome (ARDS) is higher than that in healthy controls." (PMID 35559024, 2022). "Another study comparing acute respiratory distress syndrome (ARDS), cystic fibrosis, and COPD suggests that S100A8 and S100A9 are linked to chronic inflammation while S100A12 is linked to acute inflammation." (PMID 26464846, 2013). "S100A12 had been identified as an effective inflammatory biomarker of poor prognosis in the familial Mediterranean fever, acute respiratory distress syndrome (ARDS), hemodialysis, SSc-ILD and so on." (PMID 35185901, 2022). "S100A12 is strongly expressed in the early stages of ALI and early acute respiratory distress syndrome (ARDS)." (PMID 34239729, 2021). "A previous study has reported that S100A12 levels in the lung, bronchoalveolar lavage fluid (BALF), and serum were increased in acute respiratory distress syndrome (ARDS) patients compared to healthy controls." (PMID 34368225, 2021).
cystic fibrosis (10 papers, 2013 to 2022). Autosomal recessive disorder caused by pathogenic variants in the CFTR gene (cystic fibrosis transmembrane conductance regulator), which encodes a chloride and bicarbonate channel expressed in epithelial cells, and follow the diagnosis criteria. "As an emerging biomarker for inflammatory diseases, the level of S100A12 in serum can reflect the systemic inflammatory status in acute otitis media, cystic fibrosis, respiratory distress syndrome, and dermatomyositis-associated interstitial lung disease." (PMID 34457122, 2021). "S100A12 is widely expressed in the local inflammatory site of cystic fibrosis." (PMID 35559024, 2022). "Moreover, it was demonstrated that despite similarly elevated levels of S100A8/A9, S100A12 was more increased in ARDS compared to levels in BALF obtained from cystic fibrosis patients." (PMID 23874727, 2013). "Moreover, the intense local expression of S100A12 is indicative of a pro-inflammatory function during airway inflammation in cystic fibrosis, suggesting that this protein may serve as a new target for therapies." (PMID 36235175, 2022).
gastric cancer (10 papers, 2009 to 2024). A primary or metastatic malignant neoplasm involving the stomach. "Again, the gene expression of S100A12 has been linked to worse outcomes in larger bladder, esophageal and gastric cancer materials." (PMID 38594742, 2024). "Low expression of S100A12 can be used as a marker of tumorigenesis and progression in gastric cancer." (PMID 37284310, 2023). "S100A12 is dysregulated in many types of cancers, upregulated in colorectal cancer and papillary thyroid cancer but reduced in gastric carcinoma and oropharyngeal squamous cells." (PMID 33815482, 2021). "In contrast, S100A12 mRNA and protein expression was reduced in gastric carcinoma (GC) tissues compared with normal control tissues and was correlated with TNM stage, tumor size and poor survival." (PMID 32015423, 2020). "We analyzed the binding of S100A12 to the cellular surface of human gastric carcinoma MKN74 cells in RPMI-1640 and F12 medium." (PMID 19386136, 2009). "The expression of S100A12 has been examined in the setting of gastric cancer (GC)." (PMID 32184815, 2020). "In addition, S100A12 has been found to be markedly decreased in gastric carcinoma tissues and related to pathological characteristics, tumor size, TNM stage and tumor cell invasion and differentiation." (PMID 32015423, 2020). "However, S100A12 expression was reduced in gastric cancer epithelia when compared to noncancerous gastric epithelial cells." (PMID 32184815, 2020).
idiopathic pulmonary fibrosis (10 papers, 2013 to 2025). Idiopathic pulmonary fibrosis (IPF) is a nonneoplastic pulmonary disease that is characterized by the formation of scar tissue within the lungs in the absence of any known cause. "The current association of S100A12 with depression and lung fibrosis presents an intriguing possibility of linking these findings to research on the lung-brain axis." (PMID 40655156, 2025). "Furthermore, the authors found unusual levels of certain genes in the red module associated with idiopathic pulmonary fibrosis, specifically S100A12, S100A9, CLEC4E, CRIP1, and IL1R2." (PMID 40782499, 2025). "In the peripheral blood of SSc‐ILD patients, upregulated genes including S100A8, S100A12, ADAMTS2, IFNG, and SERPINB2 were identified, which have been linked to the progression of lung fibrosis." (PMID 40165483, 2025). "In addition, we identified the key target S100A12 and its potential pathways where exercise affects pulmonary fibrosis and depression by analyzing the GEO dataset." (PMID 40655156, 2025). "Further studies are needed to explore whether S100A12 is involved in this interaction and how it might contribute to the integrated response of the lung-brain axis in the context of pulmonary fibrosis and depression." (PMID 40655156, 2025). "The role of S100A12 in pulmonary fibrosis is still worth investigating." (PMID 34368225, 2021). "A group of eight proteins has recently been propose as disease progression serum markers in Idiopathic Pulmonary Fibrosis (IPF): KL-6, surfactant protein A, and MMP-7, CCL-18, S100A12, IL-8, ICAM-1 and VCAM-1." (PMID 24216293, 2013). "We hypothesized that proteins previously shown to be elevated in patients with pulmonary fibrosis (Amphiregulin, MMP-9, MMP-7, P-selectin, S100A12, and CXCL12) would be elevated in patients who develop fibroproliferative ARDS." (PMID 39106254, 2024). "Additionally, a molecule associated with immune and oxidative stress pathways, namely S100A12 (also known as Calgranulin C or EN-RAGE), was discovered to be elevated in peripheral blood mononuclear cells of individuals with pulmonary fibrosis-related PH." (PMID 38256318, 2023). "Interestingly, the present findings indicate that the expression of DEmRNA S100A12 and S100A9 in the green module related to interstitial pulmonary fibrosis was abnormal, S100A9 expression was reduced in T/NKT cells and B-cells, while S100A12 expression was increased in monocytes." (PMID 40782499, 2025).
mastitis (9 papers, 2008 to 2025). Inflammation of breast tissue during lactation or postpartum due to an obstructed duct or infection. "We predicted a protein interaction network involving SLC11A1 interacting with 10 proteins, of which SPI1, NOD2, TLR2 and S100A12 have been reported as candidate genes associated with mastitis resistance." (PMID 40427248, 2025). "This was followed by ACKR1, MT2A, and S100A12, which are associated with mastitis and mastitis response." (PMID 39333243, 2024). "S100A12 has been shown to enhance the antimicrobial capacity of dairy cows, helping to clear mammary tissue of infection, and can be used as a diagnostic indicator of subclinical mastitis in dairy cows." (PMID 40427248, 2025). "SLC11A1 was closely associated with the expression of genes involved in the regulation of the immune response and inflammation, with S100A12, NOD2, TLR2 and SPI1 being closely associated with mastitis resistance." (PMID 40427248, 2025). "There was also a strong correlation between somatic cell count, a widely used measure of mastitis, and the level of S100A12 in milk from a herd of dairy cows." (PMID 18513449, 2008). "Finally, we predicted the SLC11A1 protein interaction network and found that SPI1, NOD2, TLR2 and S100A12 interacted with SLC11A1 and were reported as candidate genes associated with mastitis resistance." (PMID 40427248, 2025). "In cows, S100A12 is a marker for inflammatory responses and subclinical mastitis." (PMID 36851411, 2023). "This suggests that in the context of mastitis, upregulation of S100A8, S100A9, and S100A12 enhances the production of pro-inflammatory cytokines and Chemokines to maintain host homeostasis." (PMID 41156687, 2025). "In a dairy herd there was significant correlation between the level of milk S100A12 and SCC, a widely accepted indicator of mastitis." (PMID 18513449, 2008). "Thus, S100A12 protein levels in milk could be used as an indicator of mastitis in dairy cattle." (PMID 18513449, 2008). "In the present study, proteins S100A12, S100A8 and S100A9, were up-regulated by 11.17, 5.1 and 5.1 folds in the mastitis-infected mammary glands, which is consistent with the previous report, further demonstrating their roles in the immune response to pathogen infection." (PMID 25273983, 2014).
acute coronary syndrome (8 papers, 2009 to 2025). Signs and symptoms related to acute ischemia of the myocardium secondary to coronary artery disease. "S100A12 was shown to be correlated with the onset of acute coronary syndrome and serves as a promising prognostic biomarker for adverse events in patients with heart failure." (PMID 35722095, 2022). "It was found that the average sRAGE and S100A12 levels are significantly higher in patients with acute coronary syndrome than in the control group." (PMID 31275446, 2019). "In addition, S100A12 may serve as a marker of coronary plaque instability and may have therapeutic implications for treatment of acute coronary syndrome (ACS)." (PMID 34786024, 2021).
familial Mediterranean fever (8 papers, 2013 to 2025). Familial Mediterranean fever (FMF) is an autoinflammatory disorder characterized by recurrent short episodes of fever and serositis resulting in pain in the abdomen, chest, joints and muscles. "A study done by another group has demonstrated similar findings, where upregulated concentrations of S100A12 in serum were observed in patients with Familial Mediterranean fever in comparison to controls, which suggests this protein is a novel biomarker." (PMID 40948742, 2025). "High S100A12 levels have been found in the serum of active systemic juvenile idiopathic arthritis (sJIA) and familial Mediterranean fever (FMF) patients." (PMID 23718630, 2013). "Similarly, the serum concentrations of S100A12, as a novel biomarker, were shown to be upregulated in patients with Familial Mediterranean fever in comparison to controls." (PMID 29379499, 2017).
Stroke (8 papers, 2015 to 2026). Sudden impairment of blood flow to a part of the brain due to occlusion or rupture of an artery to the brain. "Our results are in validation of two small clinical studies, where elevated EN-RAGE plasma protein levels (n = 171) and S100A12 mRNA isolated from peripheral blood were associated with unfavorable 3-month functional outcome after stroke." (PMID 37794467, 2023). "Other diseases such as stroke and immunologic and infectious diseases are also associated with elevation of plasma S100A12 levels." (PMID 34977174, 2021). "In SAHLSIS2, the associations for S100A12 replicated (adjusted HR, recurrent MACE 1.25 [1.06-1.48] and stroke 1.35 [1.10-1.66])." (PMID 41614460, 2026). "S100A12 associated with Eotaxin, EGFR, MMP4 and prolactin showed good accuracy in the diagnosis of stroke." (PMID 37511304, 2023). "As comparison, in one of the original studies on stroke, a 9-gene signature was derived, including S100A12, ARG1 and MMP9 of our BRGs." (PMID 28771541, 2017). "Human stroke genomic biomarker studies have identified a common panel of five genes responding to AIS in the peripheral blood: arginase 1 (ARG1), lymphocyte antigen 96 (LY96), matrix metalloproteinase 9 (MMP9), s100 calcium-binding protein A12 (s100A12), and chemokine CC motif receptor 7 (CCR7)." (PMID 26515089, 2016).
type 2 diabetes (8 papers, 2009 to 2024). "In this study, we found that the serum concentration of S100A12 is significantly elevated in patients with type 2 diabetes." (PMID 38954262, 2024). "Our study is the first to investigate RAGE-score and S100A12 in relation to outcome in a population-based sample of patients with type 2 diabetes." (PMID 26216409, 2015). "We found plasma levels of S100A12 and RAGE-score being associated with amputation-free survival and development of PAD during a mean of 12-year follow up period in patients with type 2 diabetes." (PMID 26216409, 2015). "This association with vascular risk supports previous reports of low sRAGE and high S100A8/A9 and S100A12 levels in patients with type 1 and type 2 diabetes, and essential hypertension." (PMID 19284577, 2009). "A previous study reported an increase in the protein levels associated with the interaction between S100A12 and RAGE in Type 2 diabetes patients compared to normal controls, possibly due to increased oxidative stress caused by persistent hyperglycemic conditions." (PMID 35778422, 2022). "Higher plasma levels of S100A12 and the combined effect (RAGE-score) of esRAGE, carboxymethyl-lysine and S100A12 seem to be associated with shorter PAD- and amputation-free survival in patients with type 2 diabetes." (PMID 26216409, 2015).
viral infection (8 papers, 2018 to 2025). "Finally, a similar pattern was found for the expression of the genes S100A12 and TCRɣδ, in which they were highly expressed in the bacterial forms of infection and lowly expressed in the viral infections." (PMID 38892107, 2024). "In addition, the patient group with mixed bacterial and viral infection also had significantly elevated S100A12 expression compared to the control group (p < 0.046 for all the comparison)." (PMID 34108608, 2021). "The role of S100A12 in parasite and viral infections is also difficult to study in traditional animal models due to the lack of S100A12 expression in rodents." (PMID 29665827, 2018).
Arthritis (7 papers, 2009 to 2024). Inflammation of a joint. "S100A12 facilitates the damage and erosion of joints and is associated with the pathological process of joint inflammation." (PMID 35796625, 2022). "Given that the RAGE pathway has been suggested to be important in systemic amyloidosis, the potential S100A12-RAGE-SAA1 cascade may exist in pigs with arthritis caused by HPS infection." (PMID 19196461, 2009). "Significant (P < 0.05) increases in serum S100A12 concentrations were seen in each of the arthritis groups compared to healthy controls (60 ± 20 ng/mL), with the highest concentrations seen in RA patients (340 ± 90 ng/mL)." (PMID 22811950, 2012). "One study has examined the patterns of serum S100A12 in adult patients with these types of arthritis." (PMID 22811950, 2012). "S100A8/A9 and S100A12 serum levels were elevated not only in patients with active joint inflammation but also patients with inactive joint inflammation but active uveitis, indicating that this may be a systemic marker of ongoing immune response rather than a specific disease group." (PMID 34438537, 2021).
autoimmune disease (7 papers, 2015 to 2024). A disorder resulting from loss of function or tissue destruction of an organ or multiple organs, arising from humoral or cellular immune responses of the individual to their own tissue constituents. "Conversely, another study highlights consistently elevated levels of S100A12 proteins, present in several autoimmune diseases, in patients with active uveitis underlying JIA." (PMID 38474052, 2024). "S100A8/A9 (calprotectin) and S100A12 proinflammatory mediators are found at inflammatory sites and in the serum of patients with inflammatory or autoimmune diseases." (PMID 27057553, 2015). "As JIA and AS are believed to be autoimmune disorders the immune system mistakenly attacks the body’s own tissues, leading to inflammation and harm to the joints, it suggests that S100A12 might have a significant role in the development of AS and IBD." (PMID 38433839, 2024). "Thus, elevated S100A8/A9 and S100A12 levels serve as activity biomarkers of diverse autoimmune diseases." (PMID 34783307, 2021). "Serum levels of S100A12 and S100A8/A9 were shown to be increased in various inflammatory and autoimmune diseases, and complement activation was reported to occur at sites expressing S100A8/A9." (PMID 37146011, 2023).
Alzheimer disease (6 papers, 2010 to 2022). A progressive, neurodegenerative disease characterized by loss of function and death of nerve cells in several areas of the brain leading to loss of cognitive function such as memory and language. "Among them S100B, S100A6, S100A9 and S100A12 have been linked to Alzheimer's Disease." (PMID 20672051, 2010). "Actually, S100A12 can be secreted from glial cells and its expression is obviously enhanced under some pathological conditions, like Alzheimer's disease." (PMID 30548434, 2019). "S100A12 expressions are up‐regulated significantly in brain tissues of patients with Alzheimer's disease." (PMID 30548434, 2019). "However, the S100-A12 protein (EN-RAGE) is the least studied S100 protein in the context of Alzheimer’s disease and dementia." (PMID 36085081, 2022). "These S100 family members, namely S100A1, S100A6, S100A7, S100A8, S100A9, S100A12, and S100B, seem to be involved in the progression of Alzheimer’s disease (AD), including the formation of amyloid aggregates, and could thereby be promising regarding new therapeutic approaches." (PMID 32722137, 2020).
breast cancer (6 papers, 2015 to 2024). A primary or metastatic malignant neoplasm involving the breast. "Elevated levels of S100-A12 have been reported in humans with autoinflammation, during local and systemic inflammation and in dogs with canine mammary tumors." (PMID 34316222, 2021). "Considering the association of high S100A12 and S100A8/A9 with worse prognosis in breast cancer and other types of cancer, this could be a contributing factor to the observed difference in survival in previous observational studies." (PMID 38468349, 2024). "Several DAMPs have been linked to postoperative immune suppression and infectious complications (High mobility group box 1 (HMGB1) and Heat shock protein 70 (HSP70)), and breast cancer (alarmins S100A8/A9 and S100A12)." (PMID 38468349, 2024).